GPX4 (glutathione peroxidase 4)
Diseases named in the same sentence as GPX4 in open-access papers (continued):
Sharing a sentence is not in itself a finding about the gene and the disease.
cancer (continued). "This means that even if a patient is evaluated as having low expression of both GPX4 and FSP1, there may be cancer cells with relatively high expression of both GPX4 and FSP1, and these cells may affect the outcome of cancer treatment strategies with ferroptosis." (PMID 39594843, 2024). "Since the selenoenzyme GPX4 is a critical component of the antioxidant machinery in TNBC cells, the possible involvement of SLC38A5 in the delivery of selenium into cancer cells in the form of Se-Met could represent a novel function of the transporter in promoting cancer growth." (PMID 38539825, 2024). "As highlighted by Nakamura and Conrad, simultaneous targeting of multiple ferroptosis-related pathways, such as the GPX4 and FSP1 axes, may provide a more potent strategy for ferroptosis induction in cancer cells, particularly in therapy-resistant malignancies." (PMID 39516467, 2024). "Since the selenoenzyme GPX4 is a critical component of the antioxidant machinery in TNBC cells, the possible involvement of SLC38A5 in the delivery of selenium to cancer cells in the form of Se-Met may represent a novel function of the transporter in promoting cancer growth." (PMID 38785550, 2024). "Interestingly, although many ferroptosis regulators such as GPX4, SLC7A11, and FTH1 are obviously increased in certain cancers compared with normal tissues, the treatments targeting these regulators might vary in effectiveness across different cancers." (PMID 38169587, 2024). "Interestingly, some cancer cell lines did not undergo ferroptosis in the presence of GPX4 inactivation, suggesting the existence of other anti-ferroptotic mechanisms, and the FSP1–NADH–CoQ10 axis is one of them, paralleling the GPX4 pathway play a role." (PMID 38265475, 2024). "Notably, NCI677397 resulted in redox imbalance because it destabilized the GPX4 and DHFR proteins, which might be the substrates of USP24, producing excessive levels of oxidized lipids that drove cancer cells toward ferroptosis." (PMID 38140768, 2024). "Additionally, oxidative stress levels are elevated in cancer cells, which is compensated by the upregulation of antioxidant factors like ferroptosis suppressor protein-1 (FSP-1), solute carrier family 7 member 11 (SLC7A11) and glutathione peroxidase 4 (GPX4)." (PMID 38603713, 2024). "The Cancer Genome Atlas (TCGA) and Genotype-Tissue Expression (GTEx) database profiling analysis showed that expressions of ferroptosis suppressors, including SLCA711, GPX4, and FTH1, were also significantly increased in OV compared with healthy ovarian tissues." (PMID 38842940, 2024). "Additionally, GPX4 modulates ferroptotic cell death triggered by various ferroptosis inducers, but not other cell death types induced by non-ferroptosis inducers in cancer cells." (PMID 39614322, 2024). "Thus, dual repression of GPX4 and FSP1 by curcumin is considered promising cancer therapy." (PMID 39309443, 2024). "Additionally, the Vk variants were also shown to prevent ferroptosis in human cancer A375 and 786-O cell lines lacking GPX4 expression and rescued RSL3-induced GPX4 inhibition in fibrosarcoma HT-1080 cells." (PMID 39309484, 2024). "Accordingly, a deficiency of POR promoted resistance to ferroptosis triggered by different ferroptosis-inducing agents, named FINs, in a wide range of cancer cells and lowered lipid peroxide levels without affecting the amounts of GPX4 or glutathione and cell phospholipid profiles." (PMID 38539832, 2024). "In cancer cells, the BRD4 inhibitor JQ1 induces ferroptosis by enhancing the expression of an HDAC named SIRT1, which decreases the H3K27ac level at upstream of BRD4, ultimately affecting the recognition of acetylation sites on the histones at GPX4 and SLC7A11 genes." (PMID 37229485, 2023).
cancer (continued). "In support of this hypothesis, a previous study has revealed that ZEB1, a transcription factor that enhanced cancer metastasis by inducing EMT, promoted the sensitivity of cancer cells to ferroptosis inducers targeting GPX4 via regulating cellular lipid metabolism." (PMID 37311754, 2023). "GPX4 knockdown increases apoptosis and inhibits proliferation in non-cancer and cancer cells." (PMID 37749074, 2023). "It was found the GPX4 inhibitors could decrease the killing efficiency of CD8+ T cells at a concentration which did not affect the growth of cancer cells." (PMID 36926345, 2023). "Future studies are needed to clarify whether these negative effects are (i) related to direct inhibition of GPX4, (ii) might be circumvented by compounds with superior cancer cell selectivity, and (iii) are limited to distinct cancer entities." (PMID 36658724, 2023). "In addition, GPX4 and p62 protein expressioncan be suppressed by treatments with trehalose nanoparticles comparedwith the control, while LC3-II and NCOA4 protein levels are enhancedwith dose-dependent effects on cancer ferroptosis." (PMID 38031413, 2023). "Thus, dual suppression of GPX-4 and FSP-1 is considered a promising approach to cancer treatment." (PMID 36986483, 2023). "Previous studies have proved that the treatment of several cancer types including pancreatic, lung, colorectal, and ovarian cancers, the ferroptosis inducers such as RSL3 and RSL3A augment synergistically the anticancer effects of the drug cisplatin by blocking system Xc− or Gpx4 in the body." (PMID 35408533, 2022). "Meanwhile IR may inhibit ferroptosis by inducing the expression of SLC7A11 and GPX4 as a negative feedback regulatory pathway to induce radiotherapy resistance in cancer cells." (PMID 36505465, 2022). "The results revealed that there was a marked difference for the expression of GPX4 mRNA in different cell lines, and the survival rate of cancer cells was not significantly effected when the relative mRNA and protein expression levels of GPX4 was down-regulated by AuNF probes." (PMID 36551145, 2022). "Especially for drug-resistant cancer cells, multiple experimental cancer models have demonstrated that they can be effectively killed by ferroptosis inducers, such as some small molecules and clinical drugs that target FSP1 and GPX4, deprive GSH or improve the iron pool." (PMID 35280684, 2022). "As GSH is an important co-factor of GPX4 activity, GSH depleting drugs, such as those that reduce cysteine availability or GSH synthesis (e.g., erastin, L-buthionine sulfoximine), efficiently promote ferroptosis and even enhance the effectiveness of standard anti-cancer drugs." (PMID 36613691, 2022). "As a comparison, TPCI not only inhibits GPX4 pathway, but more importantly, is capable of generating a large amount of lipid ROS through ALOX12 activation, so that it holds great potential to be universally applicable on the treatment of a large variety of cancers." (PMID 36517470, 2022). "Because METTL7B enhanced the expression of essential ROS-scavenging enzymes, SOD1, GPX4 and HMOX1 as well as their enzymatic activities, it is worthy to explore whether METTL7B could promote resistance to other anti-cancer reagents in addition to TKIs in the future." (PMID 35144642, 2022). "However, as several studies suggested, not all the cancer cells exhibit the same requirement for the cysteine/GSH/GPX4 pathway, and they can escape ferroptosis through other ways." (PMID 35912247, 2022). "Therefore, in the absence of bioavailable GPX4 inhibitors, statins stand out as candidates for the therapeutic induction of ferroptosis in highly mesenchymal and chemotherapy-resistant cancer cells." (PMID 34303383, 2021).
cancer (continued). "We further showed that, although mTORC1 inhibition is not sufficient to induce ferroptosis (likely because GPX4 protein synthesis is reduced but not totally abolished upon mTORC1 inhibition), mTORC1 inhibitors significantly sensitizes cancer cells to ferroptosis induced by FINs." (PMID 33707434, 2021). "We have shown that cancer cells that overexpress both SLC7A11 and SLC3A2 are the ones that should be considered xCT-positive, and that this pathway, through the selenocysteine biosynthesis pathway mediated production of GPX4, impacts a cancer cell’s sensitivity to various ferroptotic inducers." (PMID 33672555, 2021). "Therefore, ferroptosis in cancer can be triggered by inhibition of this enzyme, and some efforts have been made to find specific inhibitors; (1S,3R)-RSL-3 (RSL3) was the first described irreversible inhibitor of GPX4." (PMID 33167334, 2020). "RLS3 belongs to this class, which interacts with the GPX4 selenocysteine, irreversibly inhibiting the enzyme activity, as well as several exponents of the class II FINS (DPI7, DPI10, DPI12, DPI13, DPI17, DPI18 and DPI19) and altretamine, an FDA-approved anti-cancer compound." (PMID 33202971, 2020). "However, it should be noted that the response of GPX4 inhibitors in different cancer cell lines is not consistent." (PMID 33511116, 2020). "The combined pharmacological inhibition of FSP1 and GPX4 might be an effective strategy for sensitizing cancer cells, particularly cancer cells that are not sensitive to a GPX4 inhibitor alone, to ferroptosis-inducing chemotherapeutics." (PMID 33294126, 2020). "Previous studies showed that GPx4 could efficiently use other thiol compounds (cysteine, among them) as a reducing power, instead of GSH, which can explain relative insensitivity of the cancer cells to GSH depletion." (PMID 32968052, 2020). "Up-to-data, there is no any report on GPX4-MPND gene fusion in cancer." (PMID 26330360, 2015). "Therefore, this study suggests that NAT10 may exert a pro-cancer effect by modulating the nuclear factor erythroid-2, like-1(NFE2L1)-glutathione peroxidase-4(GPX4)signaling pathway in ccRCC, indicating its potential as a new therapeutic target for this malignancy." (PMID 41189569, 2025). "Notably, a whole-genome CRISPR activation screen in 2023 revealed that sex hormones can upregulate the expression of membrane-bound o-acyltransferase domains 1 and 2 (MBOAT1/2) which contribute in preventing the ferroptosis in cancer cells lacking GPX4 and FSP1." (PMID 40855044, 2025). "Indeed, by correlating lipidomics data from the Cancer Cell Line Encyclopaedia with essentiality scores derived from whole-genome CRISPR screens (DepMap), researchers found that cells with a high content of PUFA-containing lipids crucially depend on GPX4 expression to sustain viability." (PMID 38908072, 2024). "Thus, the lack of suitable in vivo GPX4 inhibitors and the predicted systemic toxicity of such compounds limit the translation of these discoveries into cancer therapies." (PMID 37435859, 2023). "GPX4 is the ferroptosis core gene, and one recent study speculated that Targeting Wnt/β-catenin signaling by using inhibitors or knocking down TCF4 inhibited the expression of GPX4 and promoted the sensitivity of cancer cells to chemotherapy-induced ferroptosis." (PMID 37031292, 2023). "However, the selectivity and potency of GPX4 inhibitors are not consistent across different cancer cells, suggesting that other factors may mediate ferroptosis." (PMID 37337630, 2023). "Emerging evidence suggests potential mechanisms (e.g., system Xc-, glutathione peroxidase 4 (GPX4), lipid peroxidation, glutathione (GSH), and iron chelators) are involved in ferroptosis, which may mediate biological processes such as oxidative stress and iron overload to treat cancer." (PMID 36009223, 2022).
cancer (continued). "However, the detailed mechanisms that drive powerful antioxidant systems of DTP cancer cells are not clear, and existing available agents based on redox regulation, such as glutathione peroxidase 4 (GPX4) inhibitors, remain challenging to translate into therapeutic uses." (PMID 35301283, 2022). "Lack of glutathione peroxidase 4 (Gpx4) in CD8+ and CD4+ T cells, the major scavenger of phospholipid hydroperoxide, induces ferroptosis and loss of protection from infection and might facilitate cancer development." (PMID 35432318, 2022). "In addition to GPX4, ferroptosis suppressor protein 1 (FSP1) is another ferroptosis inhibitor by inducing ubiquinol (CoQ10H2) generation from ubiquinone (CoQ10), and then FSP1-CoQ10-NAP(p)H pathway reduces lipid peroxidation accumulation resulting in inhibition of cancer cell ferroptosis." (PMID 36289191, 2022). "Furthermore, increased expression of SLC7A11, GPX4 or their upstream regulatory gene NRF2 not only promotes ferroptosis resistance, but is also correlated with a poorer prognosis and lower survival rate in many types of cancers, such as liver, lung and ovarian cancers." (PMID 35118067, 2021). "It will be important for future studies to understand how the cyst(e)ine-glutathione-GPX4 and FSP1-CoQ10 pathway work together to prevent cells from undergoing ferroptosis and whether the concomitant targeting of these two pathways will be an effective method for cancer therapy." (PMID 33499222, 2021). "Furthermore, we showed that AZD8055, but not rapamycin, sensitized cancer cells to ferroptosis induced by class 2 FINs, consistent with the differential effects of these mTORC1 inhibitors on 4EBP phosphorylation and GPX4 levels." (PMID 33707434, 2021). "However, it turns out that GPX4 is not the only antioxidant defense system within cancer cells." (PMID 34815796, 2021). "However, there is still not much unknown about the effects of GPx4 in earlier stages of cancer, e.g., carcinogenesis." (PMID 32414091, 2020). "Ferroptosis is a type of oxidative nonapoptotic cell death driven by glutathione peroxidase 4 (GPX4) inactivation and lipid peroxide (LPO) overwhelming accumulation, which provides a complementary solution to address apoptosis resistance in cancer treatment." (PMID 40367177, 2025). "The results of this study have two major implications: First, GPX4 and FSP1 inhibition alone was not sufficient to induce ferroptosis in all the cancer cells." (PMID 39723384, 2024). "Another key pathway parallel to GPX4 is the AIFM2-CoQ10 axis, and ferroptosis sensitizer 1 (FSEN1) can noncompetitively target AIFM2 to sensitize cancer cells to ferroptosis." (PMID 38844964, 2024). "The GPx4 protein level remained stable during RSL3‐induced ferroptosis in iNIL‐MNs, showing that the mechanism of GPx4 protein reduction observed in the cancer cell lines did not work in our iNIL‐MN model." (PMID 36595221, 2023). "Glutathione peroxidase 4 (GPX4) is an important regulatory factor of ferroptosis and is involved in the development of many cancers, but its prognostic significance has not been systematically described in LUAD." (PMID 35620733, 2022). "Nevertheless, cancer cells with no oncogenic RAS, as HT29 colon cancer cells, are sensitive to GPX4 inhibition, too, and ectopic expression of NRAS12V, KRAS12V, or HRAS12V protects RMS13 rhabdomyosarcoma cells from Erastin-induced apoptosis." (PMID 34485382, 2021). "In agreement with our findings in HCC, GPx4 inhibits cell cycle progression and decrease growth of xenograft tumors also in non-HCC cancer cells." (PMID 29515790, 2018). "In addition, our in silico analysis of the 1739 cancer cell lines and 10967 cancer patient samples revealed a significant negative correlation between LDHB and GPX4 expression, i.e., either one of the two genes is highly expressed but rarely both together." (PMID 40090955, 2025).
cancer (continued). "In summary, NADPH-FSP1-CoQ10 exists as a parallel system independent of GPX4 action, and inhibition of FSP1 may be an effective strategy to promote death of cancer cells and other diseases." (PMID 36246888, 2022). "A recent study has reported that the expression of the mitochondrial apoptosis inducing factor 2 (AIFM2) can compensate for the function of GPX4 in the human GPX4 deletion cancer cells, and it has been renamed as the FSP1 since it can inhibit ferroptosis without the involvement of GPX4." (PMID 36506935, 2022). "ML210 used in this study was developed as a more selective GPX4 inhibitor with improved physiochemical and pharmacokinetic properties, but there are no reports using ML210 treatments in in vivo cancer models and the in vivo efficacy and toxicity remain unknown." (PMID 39369284, 2025). "FSP1 gene disruption or chemical inhibition [51,] sensitizes cancer cells to other ferroptosis inducers (e.g., GPX4 inhibitors or endoperoxide-containing ferroptosis inducers), but FSP1 inhibition is typically not sufficient on its own to induce ferroptosis in cultured cancer cells [50,51,]." (PMID 38908072, 2024).